TLR4 (toll like receptor 4)
Diseases named in the same sentence as TLR4 in open-access papers (continued):
Sharing a sentence is not in itself a finding about the gene and the disease.
asthma (continued). "We hypothesized this because OVA-induced asthma enhances the expression of TLR4 in the lung, which is associated with damage-associated molecular patterns (DAMPS) after hard inflammation due to allergen contact of sensitized cells." (PMID 39000141, 2024). "In particular, single nucleotide polymorphism (SNP) alleles in the transient receptor potential ankyrin 1 (TRPA1), transient receptor potential vanilloid (TRPV1), toll-like receptor 2 (TLR2) and toll-like receptor 4 (TLR4) have been associated with asthma susceptibility and symptom severity 3–7." (PMID 37679687, 2023). "In TH2-associated asthma, NF-κB was found to be targeted by TLR4 to promote asthma exacerbation." (PMID 36582191, 2022). "In asthma, genetic analysis of TLR4 rs1927914 was found to be linked to asthma severity." (PMID 34468896, 2021). "In addition, polymorphisms of the TLR4 gene protect bakery workers from developing work-related respiratory symptoms, and SNPs on the same gene are thought to influence asthma severity." (PMID 34248677, 2021). "TLR2 and TLR4 polymorphisms were associated with various conditions such as asthma, pulmonary tuberculosis, Helicobacter pylori infection, as well as alterations in levels of high-density lipoprotein cholesterol, low-density lipoprotein cholesterol and triglycerides." (PMID 34441346, 2021). "However, we observed an indirect association between the studied TLR4 polymorphism, increased H. influenzae colonization and an asthma risk." (PMID 32650475, 2020). "Three-day old wild-type and Toll-like receptor 4 (TLR4)-deficient neonatal mice were exposed to low-dose LPS (1 μg) intranasally for 10 consecutive days prior to ovalbumin (OVA)-induced asthma to better understand the tolerogenic mechanism(s) of low-dose LPS pre-exposure." (PMID 33072079, 2020). "The associations between TLR4 genotype, bacterial colonization, and asthma were analyzed." (PMID 32650475, 2020). "Therefore, we aimed to study the effect of TLR4 polymorphism (rs4986790) on the NP bacterial colonization and the development of asthma in Finnish children." (PMID 32650475, 2020). "Despite the results obtained in TLR4-deficient mice or deficient in downstream molecules indicating that TLR4 signaling is required to induce airway hypersensitivity, some studies showed that experimental asthma is easily induced in TLR4-deficient or MyD88-deficient mice." (PMID 29867994, 2018). "HDM is a major source of allergens in allergic patients and cause allergic airway inflammation resembling human asthma in mice by facilitating barrier disruption, inflammation, and allergen sensitization of the airways through TLR4-dependent innate and acquired immunity." (PMID 23738146, 2013). "Ten hub genes (including TNF, IL5, IL13, TLR4) were linked to 339 potential therapeutic agents; the exploratory network analysis highlighted overlap between predicted miRNA-regulated hub genes and existing asthma-relevant drug targets, including approved biologics." (PMID 42042546, 2026). "However, studies have reported associations between TLR4 polymorphisms and asthma susceptibility." (PMID 40761635, 2025). "Notably, many studies were limited by small sample sizes and did not account for key environmental exposures that may influence the effects of TLR4 on asthma susceptibility." (PMID 40761635, 2025). "Nevertheless TLR4 polymorphism was more closely related to the moderate and severe atopic asthma group than the mild atopic asthma group For the Asp299Gly polymorphism the Asp allele was associated with mild atopic asthma and the Gly allele with moderate and severe asthma." (PMID 24524443, 2014). "Although existing studies (including population association analyses and animal models) have provided strong evidence for the role of TLR4 in asthma, there are still some limitations." (PMID 40672946, 2025).
asthma (continued). "Proteobacteria LPS activates Toll‐like receptor 4 (TLR4), triggering inflammatory cascades that enhance IL‐8—a potent neutrophil chemoattractant of asthma exacerbations." (PMID 41185941, 2025). "Previous studies have found that TLR4, as an important pattern recognition receptor, can trigger and exacerbate the progression of asthma, and the TLR4‐MyD88 pathway was involved in asthma‐related signal transduction." (PMID 39803223, 2025). "Further studies are needed to clarify the functional impact of TLR4 variation in asthma pathophysiology." (PMID 40761635, 2025). "In the mouse asthma model, polydatin significantly alleviated airway inflammation, oxidative stress, and apoptosis, likely by interfering with TLR4/P2X7R-mediated signaling and suppressing the activation of the NOD-like receptor protein inflammasome." (PMID 41414033, 2025). "In pediatric asthma models, baicalin was shown to modulate the TLR4/NFκB axis, reducing proinflammatory signaling cascades, oxidative stress, and SMC abnormal proliferation." (PMID 40598285, 2025). "Toll-like receptor 4 (TLR4), whose upregulation is associated with increased inflammation in asthma." (PMID 40160461, 2025). "Toll-like receptor 4 (TLR4) plays a key role in asthma pathogenesis as a pattern recognition receptor (PRR) involved in detecting LPS triggering, innate immune, and inflammatory responses." (PMID 40761635, 2025). "In inflammatory airway diseases, such as asthma and chronic obstructive pulmonary disease, inhibition of TLR4 signaling has also been suggested to be a promising therapy by reducing neutrophil recruitment and activation." (PMID 39000141, 2024). "The expression levels of TLR4 were found to be obviously increased when a higher concentration of rHMGB1 was administrated, which is similar to in vitro study of asthma." (PMID 38414294, 2024). "miR-146a-5p is a miRNA that plays an important role in immune responses in various diseases, including asthma, regulating the immune response by suppressing the toll-like receptor 4 (TLR4)-mediated nuclear factor kappa B (NF-kB) signaling pathway." (PMID 38337625, 2024). "The complication of this enormous regulatory network hints at the involvement of TLR4 in both exogenous and endogenous inflammation, participating in infectious and non-infectious lung diseases including pneumonia, pulmonary TB, asthma, ALI, and lung cancer." (PMID 39238498, 2024). "The relationship between asthma and the TLR4/NF-κB/MyD88 signaling pathway is complex and diverse, involving the regulation of multiple immune responses and inflammatory responses." (PMID 38672467, 2024). "Bacterial and viral inflammation, signalling through TLR4 and TLR7/8, causes exacerbations of a range of different respiratory diseases, including COPD, asthma and ILDs, and plays a key role in the initiation of ARDS." (PMID 39137914, 2024). "Second, many other pathways, such as PI3K/Akt/mTOR pathway, TLR4/MyD88/NF-κB pathway, and Wnt/β-catenin pathway, are involved in the regulation of airway inflammation and remodeling in asthma." (PMID 38168709, 2024). "To further elucidate the potential mechanism of the protective effects of DEX in asthma, we explored the activation level of the TLR4/NF-κB signaling pathway in lung tissues." (PMID 36846195, 2023). "MUC1-CT reduces NLRP3 inflammasome-mediated pyroptosis by inhibiting the activation of the TLR4/MyD88/NF-κB pathway, thereby attenuating neutrophil airway inflammation in patients with asthma." (PMID 37880668, 2023). "Particularly, TLR4, one of the type I transmembrane TLRs, has been proven to play a pivotal role in the inflammatory responses in asthma." (PMID 36846195, 2023). "Intranasal administration of PAO elicited characteristic features of asthma in WT mice, whereas TLR4-KO mice exhibited reduced asthma symptoms but sustained IL-4 levels." (PMID 37426425, 2023).
asthma (continued). "Baicalin ameliorates the pathogenesis and development of pediatric asthma by upregulating microRNA-103 and mediating the TLR4/NF-κb pathway." (PMID 36814956, 2023). "Studies have revealed that TLR4/MyD88/NF-κB pathway suppression can attenuate pathological mechanisms of asthma." (PMID 37880668, 2023). "A study of the role of neutrophils in the progression of severe forms of asthma led to the finding that the stimulation of TLR4 in neutrophils with HDM regulates their apoptosis." (PMID 37629528, 2023). "Single nucleotide polymorphisms (SNP) in five different TLRs (TLR2, TLR4, TLR6, TLR9, TLR10) were described to significantly contribute to asthma susceptibility, severity, and responsiveness." (PMID 37759430, 2023). "Compared with the control group, the expression of Fos, Myl9 and Tlr4 in the asthma model was increased, while the expression of Smg7, Sumo2 and Stat5a was decreased." (PMID 36726128, 2023). "While further in-vivo studies have confirmed the involvement of TLR4 in the induction of HDM-mediated asthma, the respective studies furthermore emphasized the effects on ECs in this process." (PMID 37614946, 2023). "During the development of asthma, NF-κB is recruited by TLR4 to induce the production of several pro-inflammatory factors in the airway wall." (PMID 37451839, 2023). "Mechanistic studies revealed that MUC1 reduced NLRP3 inflammasome-mediated pyroptosis by inhibiting TLR4/MyD88/NF-κB pathway activation, thereby suppressing neutrophilic airway inflammation in patients with asthma." (PMID 37880668, 2023). "Exposure to lipopolysaccharide (LPS) has been confirmed to play a central role in the development of allergies and asthma, and the LPS-sensing protein TLR4 has been investigated for its role as a critical contributor to asthma-related pathophysiology." (PMID 37630200, 2023). "CD36+ EVs accelerate disease progression by activating inflammation through the heterodimerization of TLR4/6 in asthma." (PMID 36959535, 2023). "Particularly, Derp 2, a major component of HDM, has been proven to stimulate and augment the TLR4 pathway in asthma." (PMID 36846195, 2023). "Macrophage autophagy is implicated in the progression of asthma through several signaling pathways, such as MAPK, TLR4, and mTOR, regulating the polarization, inflammatory responses, and cell death." (PMID 37181813, 2023). "In induced sputum, asthma patients with higher total serum immunoglobulin (IgE) levels showed increased macrophage expression of TLR4." (PMID 35911120, 2022). "When TLR4 in involved, it can participate in asthma pathophysiology and treatment with probiotic has influence on the TLR4 and related signaling pathways." (PMID 35296330, 2022). "Some TLR agonists decrease Th2 responses and relieve allergic diseases; for instance, TLR2 and TLR4 agonists can alleviate asthma symptoms." (PMID 35484967, 2022). "Highly purified neutrophils (> 90%) from asthma patients and healthy controls were activated by exposure to LPS, which activates toll-like receptor 4 (TLR4) and to fLMP, which activates formyl peptide receptors." (PMID 34342773, 2022). "The aim of this study is to investigate the protective effects of glaucocalyxin A (GLA) on airways in mouse models of asthma, concerning the inflammatory mediators, Th1/Th2 subgroup imbalance, and Toll-like receptor 4 (TLR4)/NF-κB signaling pathway." (PMID 35859797, 2022). "In this work, miR-885-3p expression and toll-like receptor 4 (TLR4) expression in asthma patients’ plasma and lipopolysaccharide (LPS)-treated 16HBE cells were detected through quantitative real-time PCR." (PMID 35156897, 2022). "In recent years, the Toll-like receptor 4 (TLR4)/NF-κB signaling pathway and the airway inflammation have attracted much attention in asthma research." (PMID 35859797, 2022). "Overall, these data demonstrated that HMGB1-mediated airway epithelial cell apoptosis was correlated with TLR4/NF-κB signaling activation in the in vitro model of HDM-induced asthma." (PMID 33541260, 2021).
asthma (continued). "House dust female (HDM) is one of the major ligands of TLR4, which is ubiquitous in the air and induce acute attack of asthma." (PMID 34037898, 2021). "Ibudilast, a TLR4 antagonist, has been used in the clinic to exert an anti-inflammatory effect on asthma." (PMID 34025417, 2021). "Our study suggests a mechanism by which evodiamine hinders the development of asthma in rats by altering expression of TLR-4, NF-κB, MyD88, and HMGB1, thus hindering airway remodelling in the rat lung." (PMID 33577738, 2021). "Studies have shown that the HMGB1/TLR4 signaling pathway is abnormally activated in mouse models such as asthma and allergic rhinitis." (PMID 34007295, 2021). "HMGB1 is upregulated in the airways in asthma and potentiates airway smooth muscle contraction via TLR4." (PMID 33925132, 2021). "For example, interference with the HMGB1/TLR4 signaling pathway suppresses airway inflammation in asthma." (PMID 34007295, 2021). "GPR30 activation has been shown to mediate anti-inflammatory protective effects in neuroinflammation, vascular inflammation, and asthma and decreased the expression of TLR4 in murine macrophages induced by LPS." (PMID 33995086, 2021). "For another, TLR4 is an acknowledged receptor generally expressed on airway epithelial cells triggered by endogenous danger signals in asthma pathophysiology." (PMID 33541260, 2021). "The S100A9 protein binds to the proinflammatory receptors involving RAGE and TLR4, both of which are involved in the pathogenesis of asthma." (PMID 33791048, 2021). "Our finding of a significantly lower level of IL-6 and IL-1B in response to HDM and LPS in the asthmatic group is in concordance with the previous study that reported lower expression of TLR4 in asthma." (PMID 34220812, 2021). "It has been reported that HMGB1 critically participates in inflammatory development of asthma by acting as a ligand of TLR4." (PMID 33541260, 2021). "S100A9 protein binds to the proinflammatory receptors, receptor for advanced glycation end products (RAGE) and Toll-like receptor 4 (TLR4), both of which are involved in the pathogenesis of asthma." (PMID 33791048, 2021). "Our results warrant further studies on the impact of host TLR4 genetics on the early bacterial colonization and development of asthma in different populations." (PMID 32650475, 2020). "It has been found that HMGB1 is associated with increased airway smooth muscle contraction and TLR4 activation in asthma." (PMID 31958320, 2020). "Further, ablation of TLR4 on epithelial cells or inhibition through antagonists reduced recruitment and activation of sub-epithelial DCs and suppressed features of asthma such as bronchial hyperreactivity." (PMID 33424827, 2020). "Poly-γ-glutamic acid inhibited allergic lung inflammation through the Toll-like receptor-4-dependent pathway in a mouse model of asthma, and glutamic acid has been recommended for asthma patients." (PMID 30823378, 2019). "Our later works demonstrated experimental evidence supporting possible roles of IL10 and TLR4 in comorbid asthma and hypertension." (PMID 31705029, 2019). "The role of TLR4 in asthma has been extensively studied while the involvement of other TLRs in asthma has gained less attention." (PMID 29867994, 2018). "In conclusion, paeonol ameliorated OVA-induced asthma through the TLR4/NF-κB and mitogen-activated protein kinase (MAPK) signaling." (PMID 30186353, 2018). "TLR4 carriers vs. WT had lower odds ratio (OR) of asthma-related emergency room (ER) visits in the past 12-months (0.39 [0.15, 0.97]) in an unadjusted model." (PMID 30140039, 2018). "Stimulation of TLR4 on MC exacerbates murine experimental asthma and upon LPS inhalation IL-5 production increases." (PMID 29867994, 2018). "Based on these findings we shall discuss more specifically the involvement of different TLRs in asthma with a special focus on TLR4." (PMID 29867994, 2018).
asthma (continued). "The phenomenon that paeonol suppressed TLR4 expression was also observed in OVA-induced asthma model of our study." (PMID 30186353, 2018). "Contact with small animals such as cats and dogs especially those that are held in house (indoor) can significantly exacerbate asthma through stimulation of TLR4 signaling." (PMID 29867994, 2018). "We first examined the relationship of genotype and asthma at the individual SNP/gene level (TLR4, CD14, TIRAP, and TNFα)." (PMID 30140039, 2018). "The aim of this study was to evaluate the contribution of TLR4 in S1P-dependent asthma-like disease in mice." (PMID 29093714, 2017). "In both asthma groups, a greater percentage of TLR4 expression was observed in monocytes/macrophages than neutrophils in both induced sputum and peripheral blood." (PMID 27084682, 2016). "The percentage of macrophages expressing TLR4 in induced sputum was significantly higher in asthma with high total serum IgE versus asthma with normal total serum IgE." (PMID 27084682, 2016). "Epidemiological studies have evaluated numerous polymorphisms in TLR2, TLR4 and CD14 in relation to asthma and similar phenotypes and some were significantly associated with high asthma prevalence, risk or severity." (PMID 27495363, 2016). "Targeting TLR4 to treat asthma is based on the activation of TLR4 as an adjuvant in allergy vaccines to induce tolerance and inhibition of TLR4 expression." (PMID 27274620, 2016). "For instance, in asthma, the presence of TLR4 is lowered in the respiratory tract, whereas TLR4 expression is elevated in COPD patients, possibly as a result of the cellular breakdown in the airways." (PMID 26617525, 2015). "Expression of TLR2 and TLR4 as well as that of the pro-inflammatory cytokines IL-8 and IL-1 increased in subjects with neutrophilic asthma as compared with that in other asthma subtypes and controls." (PMID 25760938, 2015). "In particular, TLR2 and TLR4 are regarded as the major TLRs responsible for sustaining the inflammatory responses in both asthma and COPD." (PMID 26617525, 2015). "HDM allergens trigger allergic inflammation via Toll-like receptor (TLR), C type lectin receptor, NOD-like receptor and proteinase-activated receptor signaling pathways, and TLR4 in the TLR signaling is important in HDM-induced asthma." (PMID 25973752, 2015). "TLR2 ligands were also able to inhibit Th2 responses in house dust mite allergic patients and TLR4 signaling by LPS suppressed asthma-like responses in mice." (PMID 25973430, 2015). "Genetic variations in TLR1, TLR2, TLR4, TLR6 and TLR10 have been associated with the development of asthma." (PMID 24524443, 2014). "Tlr3 contributes to asthma exacerbations in mice and a study in a murine macrophage cell line suggested a pro-inflammatory role of Tlr4 and 5 in the disease." (PMID 24735374, 2014). "Relations between CD14 C-159 T, TLR4 299 and TLR4 399 genotypes and duration of asthma history of allergic rhinitis-dermatitis, total IgE, eosinophil, skin prick test, forced expiratory volume 1 (FEV1) and severity of disease were evaluated." (PMID 24524443, 2014). "LPS is an abundant environmental agonist of TLR4, a receptor important for cellular responses to several asthma-relevant allergens." (PMID 25628603, 2014). "It has also been observed that mice exposed to ozone and LPS develop asthma as a result of the activation of TLR4 on the surface of inflammatory cells." (PMID 24581224, 2014). "As DCs express TLR4 and considering the crucial role of these cells in the initiation and maintenance of adaptive Th2 responses in asthma, it was originally considered that the direct TLR4 activation of DCs is the key event to initiate the Th2 polarization." (PMID 23724247, 2013). "In a similar way, Th2 sensitization to inhaled ovalbumin (OVA), an antigen often used to induce asthma features in mice but often criticized for its content in LPS, seems to depend on recognition by stromal TLR4." (PMID 21943186, 2011).